MYC (MYC proto-oncogene, bHLH transcription factor)
Diseases named in the same sentence as MYC in open-access papers (continued):
Sharing a sentence is not in itself a finding about the gene and the disease.
lung carcinoma (continued). "Notable ORFs enriched in metastatic tissues include GNAS and MYC, which were previously shown to promote KRAS-driven lung cancer metastasis." (PMID 30013058, 2018). "Demonstration of two selected PPIs, MYC/NSD3 and STK11/CDK4, under endogenous conditions in multiple lung cancer cell lines strongly supports the validity of the OncoPPi network data set for further examination." (PMID 28205554, 2017). "In the present study in lung cancer, LINC00152 knockdown leads to reduced several cell growth-related proteins such as STAT3, p38α, CREB1, STAT1, c-MYC and CCNE1." (PMID 28592840, 2017). "In lung cancer cell lines it was shown that through TMEM209 stabilization of NUP205, protein levels of MYC were increased and promoted cell growth." (PMID 27115612, 2016). "Restoration of miR-145-5p expression using either vorinostat or 5-azacytidine, which released methylation of the miR-145 locus, led to inhibition of migration of lung cancer cells and to down-regulation of OCT-4, MYC, EGFR, MUC-1 and TPD52 expression." (PMID 26440147, 2015). "Using an EGFR mutant lung cancer cell line, we showed that inhibition of EGFR leads to a reduction in miR-9 as well as c-MYC expression." (PMID 23365639, 2013). "Cigarette smoke downregulates miR-487b, which targets both RAS and MYC; RAS is also a target of miR-let-7, again downregulated in lung cancer." (PMID 24130964, 2013). "In this regard, our results demonstrated that silencing of SOX2 significantly reduces the protein expression level of oncogenes-WNT1, WNT2, c-MYC and NOTCH1 in human lung cancer and further revealed other target cancer genes of SOX2." (PMID 22615765, 2012). "In lung cancer, KRAS, MYC, EGFR, and ERBB family are well-known oncogenes, and all of them were found to be highly significant in copy number gains." (PMID 21829676, 2011). "CONCLUSION: In this retrospective cohort of lung carcinoma patients, high c-MYC expression, but not EZH2 expression, was independently associated with poor OS after adjustment for clinical factors." (PMID 41928013, 2026). "Furthermore, screening for oncogenic protein-protein interactions in lung cancer cells identified a physical interaction between NSD3S and the MYC oncoprotein via its PWWP domain, which enhances MYC transcriptional activity." (PMID 41301842, 2025). "IHC staining of paired adjacent non-tumor and lung cancer tissue samples from patients showed markedly elevated expression of MYC and SKP2 in cancerous tissues." (PMID 41241099, 2025). "Similarly, lung cancers are mostly suppressed by miR-184 via EPAS1, CDC25A, and c-MYC targeting, although chemotherapy resistance studies reveal occasional tumour-promoting roles." (PMID 41379397, 2025). "The activation of MYC target gene signatures is also present in SCCOHT tumors, and in BRG1-null lung cancer cell lines, the reintroduction of BRG1 antagonizes MYC function, pointing to a connection between BRG1 and MYC that may resemble that of SNF5." (PMID 40647552, 2025). "Also in lung cancer, oncogenic KRAS allows for irreversible MYC overexpression, thereby driving cytosolic phospholipase A2 activity to release membrane-bound arachidonic acid and activate lipoxygenase and cyclooxygenase pathways." (PMID 39113608, 2024). "The results showed that miRNA may be involved in the regulation of several lung cancer driver genes, such as BCL2, CYCS, E2F2, MCL1, or MYC, among others." (PMID 38791013, 2024). "In AKT1 (r = −0.15, p < 0.05), BRAF (r = −0.25, p < 0.05), GAPDH (r = −0.3, p < 0.05), KRAS (r = −0.24, p < 0.05), MYC (r = −0.25, p < 0.05), and SRC (r = −0.24, p < 0.05), stromal score was negatively correlated with lung cancer and the highest correlation coefficient was in GAPDH." (PMID 39734333, 2024). "Notably, our study identified a negative correlation between the expression of key hub genes (AKT, BRAF, GAPDH, KRAS, MYC, and SRC) and immune and stromal cell content in the lung cancer TME." (PMID 39734333, 2024).
lung carcinoma (continued). "On the other hand, oral administration of chia extracts for five months significantly reduced lung cancer biomarkers, including the relative weight of the lung, ICAM-1, c-MYC, and MMP9 gene expression, and lung histology was improved considerably compared to the lung cancer control one." (PMID 39338293, 2024). "TERT and MYC status was analyzed using digital PCR (dPCR) in tumor and adjacent non-tumor tissue samples of 114 lung cancer patients." (PMID 37858127, 2023). "Thus, using the OR combination for TERT and MYC, a total of 68 lung cancer tissues were identified correctly, 16 samples by TERT, 25 by MYC, and 27 by both markers." (PMID 37858127, 2023). "But when we integrated the single cell RNA sequencing data to identify the potentially regulators in lung cancer, we found that MYC was not a strong candidate target." (PMID 36681772, 2023). "GSEA analysis in the present study showed enrichment of the MYC target, suggesting that TXN may target the MYC protein through the MAPK signaling pathway, promoting the occurrence and development of lung cancer." (PMID 36776308, 2023). "Amplification of MYC and TERT is a common event in lung cancer." (PMID 37858127, 2023). "Due to the roles of MYC and TERT in lung cancer, the aims of this study were the verification of our recent results analyzing MYC CNV in tumor and non-tumor tissue of lung cancer patients using an independent study group and the assessment of TERT CNV as an additional marker." (PMID 37858127, 2023). "We demonstrated that amplification of MYC and TERT is a common event in lung cancer patients." (PMID 37858127, 2023). "Stabilization of these onco-proteins during CPPD exposure indeed depends on USP28, as the lung cancer cell line SK-MES1 (SCC), which is mutant for USP28 and expresses low levels thereof, showed some degree of c-JUN or c-MYC destabilization after CPPD treatment." (PMID 34611298, 2022). "On the other hand, the genomic alteration/mutation analysis of the hub-DEGs reflected that most mutation for the EGFR occurred across the four lung cancer studies and was followed by the MYC and CHEK1 genes, since EGFR is a highly mutant/altered gene for lung cancer and NSCLC as well." (PMID 35632527, 2022). "Consistent with the fact that MYC serves as a widespread transcription factor that can regulate tumor‐specific gene expression, we also found the decreased expression of its target gene PD‐L1 in both CDK16‐KD lung cancer cells." (PMID 34687270, 2022). "Recent studies on lung cancer revealed that c-MYC is a key downstream effector of FGF/FGFR-dependent signaling in response to oxidative stress, and that FGFR inhibition induced apoptosis through c-MYC downregulation." (PMID 34830951, 2021). "In lung cancer, SMARCA4 inactivation affects about one-third of non-small cell lung cancers (NSCLCs) and preferentially occurs against a background of wild type MYC (either C, L or N) or of members of the MYC-axis, such as MAX or MGA4–7." (PMID 34262032, 2021). "It has been reported that c-MYC and MYCN are amplified and/or overexpressed in lung cancer." (PMID 34235156, 2021). "We tested the effects of GSK-J4 on the growth of our panel of cancer cells and found that the drug was more toxic in the SMARCA4def cells, with a five-fold lower EC50 than in the MYCamp cells or in the lung cancer cells that are wild type for both SMARCA4 and MYC." (PMID 34262032, 2021). "Similarly, circRNA_103809 enhances the ability of lung cancer cells to invasively grow by binding miR-4302, which suppresses ZNF121-dependent expression of the MYC gene." (PMID 34440124, 2021).
lung carcinoma (continued). "Oncoprotein MYC could transcriptionally upregulate the expression of the SR protein splicing factor, SRSF1, in lung cancer cells, which triggered mRNA splicing of a series of kinases and facilitated oncogenic signaling." (PMID 35096927, 2021). "The results indicated that CPF impeded cell cycle re‐entry in quiescent lung cancer cells by reduction of FACT and c‐MYC mRNA and protein levels, with concomitant decrease in H3K4 tri‐methylation and RNA polymerase II occupancy at FACT and c‐MYC promoter regions." (PMID 31960591, 2020). "TNF, EGFR, MYC, IL-6, and JUN were identified as major hub genes of HCT on lung cancer." (PMID 32595734, 2020). "In addition, translocations and inversions can also occur, positioning these genes under the control of constitutively active genes such as MYC or create chimeric proteins, such as the ALK-EML4 fusion commonly observed in lung cancers." (PMID 32850380, 2020). "For example, NELFE could promote the progression of hepatocellular carcinoma by regulating MYC signaling, and TTP could inhibit cell proliferation and accelerate cell death in lung cancer through the autophagy pathway." (PMID 33193734, 2020). "The aim of our study was the assessment of dPCR for the detection of MYC CNV in primary lung cancer tissue and adjacent nontumor tissues." (PMID 33014186, 2020). "MYC status was analyzed with dPCR as well as qPCR (quantitative PCR) using gDNA (genomic DNA) from tumor and adjacent nontumor tissue samples of lung cancer patients." (PMID 33014186, 2020). "A previous study has reported that MYC, SUZ12, and KRAS are the biotargets of miR‐487b in cigarette smoke‐induced lung cancer, leading us to speculate that miR‐487b could also suppress CRC tumorigenesis by inhibiting these three genes." (PMID 30791232, 2019). "The specific overexpression of MYC in the Basal/SCC-like subtype combined with activity in its closest corresponding subtypes of breast- and lung cancer may warrant pre-clinical testing of this agent in Basal/SCC-like bladder cancer." (PMID 29487377, 2018). "We further show here that high GATAD2B expression correlates with worsened outcomes in lung cancer patients and cooperates with KRAS to promote gain-of-function pro-oncogenic and pro-metastatic transcriptional programs including MYC to mediate cell invasion in vitro and tumor progression in vivo." (PMID 30013058, 2018). "Indeed, differences in glucose and glutamine metabolism were recently uncovered between MYC‐ and MET‐induced liver tumors and between MYC‐induced liver and lung cancer." (PMID 28923827, 2017). "Besides, miR-145 inhibits the migration and invasion of lung cancer cells via fascin homolog 1 (FSCN1) downregulation and cell growth is inhibited by miR-145, while MYC has been shown to be a direct target for miR-145." (PMID 28915579, 2017). "Indeed, with our focused set of 83 lung cancer genes, we identify >260 novel interactions, expanding the PPI landscape for this gene set by >200%, including for well-studied cancer genes like MYC and CDK4." (PMID 28205554, 2017). "In this context, the simultaneous down-regulation of miR-342-3p and let-7e in ALK-rearranged lung cancer might help amplify the RAS family effector signals and/or MYC activity, which could result in resistance to anti-cancer drugs." (PMID 28035073, 2017). "Neratinib with the Aurora inhibitor GSK-1070916 and neratinib with a taxane were further tested in three sets of cell lines with amplified or non-amplified MYC, from breast, colon and lung cancers." (PMID 26018524, 2015). "For example, the action of let-7 miRNA as a tumor suppressor was found to be absent in lung cancers and to promote cancer progression by inhibiting downstream translation of MYC." (PMID 26134825, 2015). "For example, the action of let-7 miRNA as an antioncogene was found to be absent in lung cancers and to promote cancer progression by inhibiting downstream translation of MYC." (PMID 25560389, 2015).
lung carcinoma (continued). "Similarly to the effect of miR-145-5p, selective knockdown of OCT-4, EGFR, MYC, MUC-1 and the newly identified TPD52 impaired migration of lung cancer cells." (PMID 26440147, 2015). "To further confirm the reciprocal relationship between HBP1 expression and β-catenin activity in lung cancer, we examined whether HBP1 knockdown would affect β-catenin/TCF activity and increase c-MYC and cyclin D1 expression." (PMID 24895061, 2014). "We selected six DNA targets commonly amplified in lung cancer including two centromeric probes (CEP3 and CEP6) and four probes to areas of frequent genomic amplification, i.e. 3q28 (TP63), 5p15.2 (D523 and D5S721 markers), 8q24 (MYC), and 7p12 (EGFR)." (PMID 19547694, 2009). "The odds of having lung cancer given that a preinvasive lesion had gain for genomic regions increased from 4.23 (1.21–14.8, 95%CI) when 1 or 2 markers of 4 (CEP3, TTP63, CEP6, MYC) were abnormal to 11 (2.63–45.9, 95%CI) when 3 or 4 markers showed elevated copy numbers." (PMID 19547694, 2009). "Here, we tested whether genomic gains in six specific loci, TP63 on 3q28, EGFR on 7p12, MYC on 8q24, 5p15.2, and centromeric regions for chromosomes 3 (CEP3) and 6 (CEP6), may provide further value in the prediction of lung cancer." (PMID 19547694, 2009). "In FGFR dependent lung cancer cells, induction of oxidative stress has been suggested to be the main mechanism responsible for lung cancer cell death following FGFR inhibition, and it has been reported that the reduction of MYC protein levels strictly determined the onset of oxidative stress." (PMID 39031286, 2024). "Strict correlation between FGF/FGFR blockade, MYC downregulation, oxidative stress and apoptosis have also been described in FGFR dependent lung cancer while neither MYC downregulation by FGF/FGFR inhibition nor oxidative stress or apoptosis was observed in FGFR independent xenografts." (PMID 39031286, 2024). "Additionally, for ovarian cancer it was shown that TERT and MYC, as well as PIC3CA, CCNE1, and KRAS, might be useful to tailor therapeutics in precision medicine, and the same might be true for lung cancer." (PMID 37858127, 2023). "In accordance, in this study the combination of MYC and TERT lead to an increase of sensitivity to 60% to detect lung cancer, suggesting that the combination of both markers could be useful for the differentiation between lung cancer and normal tissue." (PMID 37858127, 2023). "We next analyzed the protein expression of oncogenes known to be transcriptionally upregulated in tuft cell-like lung cancer subsets, i.e., BCL2, MYC, and KIT, because their expression might further delineate tuft cell-like variants and open new therapeutic perspectives." (PMID 36402755, 2022). "PD-L1-enhancing oncogenes, such as EGFR, ALK, MET, AKT, MYC, and CDK5, were not identified as hits in this study because KRAS mutations in lung cancer cell lines (H2009 and H460) could establish distinct PD-L1 regulatory axes." (PMID 36357569, 2022). "Thus, our clinical data further confirmed that LKB1 loss increased the DNA methylation and expression level of ALKBH5, which resulting in the demethylation of m6A modification on SOX2, SMAD7, and MYC, and maintaining their expression for KRAS mutant lung cancer." (PMID 34016959, 2021). "c-MYC and MYCN may be used as therapeutic targets for treating lung cancer patients." (PMID 34235156, 2021).
lung carcinoma (continued). "While it is clear that FACT can regulate c‐MYC in lung cancer cells, whether or not c‐MYC can influence FACT expression in lung cancer cells remains unknown." (PMID 31960591, 2020). "Notably, we identify MYC as a protein that is upregulated by RET expression and downregulated by treatment with cabozantinib, opening up potentially new therapeutic avenues for the combinatorial targetin of RET fusion- driven lung cancers." (PMID 33318047, 2020). "With 269 novel interactions, OncoPPi greatly expands the landscape of interactions among this selected set of lung cancer genes and defines interactions with potential significance for cancer PPI target discovery, such as CDK4/STK11, LATS2/RASSF1 and MYC/NSD3 (WHSC1L1)." (PMID 28205554, 2017). "Based on our finding that LINC00152 was mainly located in the cytoplasmic of lung cancer cells, the regulation process targeted to p38α, STAT1, CREB1 and c-MYC growth related proteins may be at the post-transcriptional level such as protein degradation mechanism." (PMID 28592840, 2017). "Interestingly, in an EGFR mutated lung cancer cell line, treatment with an EGFR inhibitor (Gefitinib) resulted in a concentration specific reduction in c-MYC and miR-9 expression while not changing let-7a expression." (PMID 23365639, 2013). "Besides, NT157 decreased expression of oncogenes BCL2, CCND1, MYB, and MYC and increased genes related to cellular stress and apoptosis, JUN, BBC3, CDKN1A, CDKN1B, FOS, and EGR1 (p < 0.05), favoring a tumor-suppressive cell signaling network in the context of lung cancer." (PMID 36224313, 2022). "Finally, RNA profiling of lung epithelial cells (BEAS-2B) expressing a mutant allele of PIK3 (E545K) identified a network of transcription factors such as MYC, FOS and HMGA1, not previously recognised to be associated with aberrant PI3K signalling in lung cancer." (PMID 22363436, 2012). "Notable, in a human lung cancer A549 cell line xenograft model in immunodeficient BALB/c nude mice, overexpression of MYC promoted tumor proliferation, but did not significantly increase the dissemination of tumor cells." (PMID 39899538, 2025). "DLX5 is methylated in early stage lung cancers, suggesting that it is only deregulated in lung cancer progression, and it is not in PAH, in which it induces the expression of MYC and β-catenin, promoting cell proliferation and metastasis." (PMID 36661515, 2023). "The activities (ssGSEA scores) of both pluripotency factors (NANOG, MYC) and mitochondrial biogenesis are higher in CSCs compared with non-CSCs in skin squamous cell carcinoma (SCC) and lung cancer (GSE108679 and GSE136580, respectively)." (PMID 37463926, 2023). "Earlier pathway-based analyses of primary lung cancers and NCI60 cell lines also did not identify direct interactions involving RAS and MYC." (PMID 28152508, 2017). "Also, all the tuft cell-like lung cancer subtypes significantly expressed BCL2 and KIT, and tuft cell-like NECs unlike non-tuft cell-like NECs overexpressed MYC." (PMID 36402755, 2022). "In addition, higher expression of the oncogenes c-MYC, WNT1, WNT2 and NOTCH1 was detected in side population (SP) cells than in non-side population (NSP) cells of A549 lung cancer cells, indicating a possible mechanism for the tumorigenic potential of CSC’s." (PMID 23349823, 2013). "Nevertheless, chelerythrine chloride was able to inhibit the growth of lung cancer cell lines from different proximal/distal origins, the β-catenin nuclear localization in several lung histologies, and β-catenin and perhaps SOX2 and MYC expression regardless of the tissue origin." (PMID 31935827, 2020).